TFEB (transcription factor EB)
Diseases named in the same sentence as TFEB in open-access papers (continued):
Sharing a sentence is not in itself a finding about the gene and the disease.
Alzheimer disease (continued). "Additionally, physical activity activated TFEB and TFEB-related processes in an animal model of Alzheimer’s disease, while long-term exercise enhanced lysosomal biogenesis in a TFEB-dependent manner in a mouse model." (PMID 39718832, 2024). "In Alzheimer’s disease models, ouabain demonstrates neuroprotective effects by activating a signaling pathway that stimulates transcription factor EB (TFEB), a key regulator of gene transcription within the autophagy–lysosome system, thus reducing tau levels in APP mice." (PMID 38892309, 2024). "Indeed, in the prodrome of transgenic mouse models of Alzheimer's disease, fibrillar amyloid (beta) stimulates the nuclear translocation of microglial TFEB, in part through sirtuin 1 (SIRT1)‐mediated deacetylation of TFEB at K116." (PMID 37728021, 2023). "TFEB has emerged as a therapeutic modulator in lysosomal storage diseases and a promising target in the treatment of neurodegenerative disorders (ND), such as Alzheimer’s disease and Parkinson’s diseases." (PMID 37834287, 2023). "Moreover, neurons from the brains of patients with Alzheimer's disease contain elevated levels of acid sphingomyelinase, which impairs the TFEB‐mediated upregulation of ATGs and induction of lysosomal biogenesis." (PMID 37728021, 2023). "Activation of TFEB-mediated lysosomal biogenesis to degrade protein aggregates is beneficial to NDs that are characterized by the accumulation of protein aggregates, including Alzheimer’s disease (AD) and Parkinson’s disease (PD)." (PMID 37191408, 2023). "In this review, we summarize the role of few transcription factors and their possible role in pathological features in Alzheimer’s disease and later with the most important and currently most studied transcription factor TFEB and its role in amyloid-beta and tau pathology." (PMID 34970114, 2021). "Impaired TFEB function bas been previously reported in neurodegenerative diseases such as Alzheimer’s disease and PD, but its potential impairment in MSA is still unknown." (PMID 31434803, 2019). "Interestingly, it has been reported that increasing autophagy via expression of TFEB has positive effects in other neurodegenerative diseases, such as Alzheimer's disease, Niemann Pick disease, and Gaucher disease by improving the degradation of protein aggregates." (PMID 34637165, 2022). "Transcription factor EB (TFEB), a major regulator of ALP, has emerged as a leading factor in addressing neurodegenerative disease pathology, including Alzheimer's disease (AD), Parkinson's disease (PD), PolyQ diseases, and Amyotrophic lateral sclerosis (ALS)." (PMID 36184826, 2023). "The central role of TFEB in the regulation of ALP activity made the transcription factor an attractive tool to treat lysosomal storage diseases, such as Alzheimer’s disease, amyotrophic lateral sclerosis, Gaucher disease, and Pompe’s disease." (PMID 35682624, 2022). "Accumulating studies have suggested that targeting transcription factor EB (TFEB), an essential regulator of autophagy‐lysosomal pathway (ALP), is promising for the treatment of neurodegenerative disorders, including Alzheimer's disease (AD)." (PMID 31858697, 2020). "A study has confirmed that the acetylation of TFEB can alleviate the pathological process of Alzheimer’s disease, a process independent of the MTORC1 pathway." (PMID 37569278, 2023). "In addition to the classical targets related to Aβ and tau protein hyperphosphorylation, lysosomal pathways, autophagy, apoptosis, transcription factor EB (TFEB), and TREM2 are also potential therapeutic pathways and targets for Alzheimer’s disease (AD)." (PMID 37214397, 2023). "Moreover, the dysregulation of TFEB and TFEB-mediated ALP contributes the pathogenesis of various neurodegenerative diseases including Alzheimer’s disease and Parkinson’s disease, while increasing TFEB expression or activation attenuates the pathogenesis of neurodegenerative diseases." (PMID 31508418, 2019).
Alzheimer disease (continued). "Previously, we have identified several TFEB activators from curcumin derivatives, one of which directly binds to and activates TFEB without inhibiting the MTORC1 pathway and it exerts neuroprotective effects in animal models of Alzheimer’s disease." (PMID 32098449, 2020). "Another study reported that TFE3 mRNA levels are higher than those of TFEB in human hippocampus tissue, and it further demonstrated that TFE3 but not TFEB plays a prominent role in promoting lysosomal biogenesis and autophagy upregulation in CA1 neurons during Alzheimer’s disease pathogenesis." (PMID 34912803, 2021).
breast carcinoma (46 papers, 2015 to 2025). "Cell and animal experiments have suggested that TFEB is a major regulator of Tumor-associated macrophages (TAM) in breast cancer." (PMID 35531069, 2022). "In breast cancer, however, the partial functional loss of TFEB by the interaction of signal transducer and activator of transcription 3 (STAT3) enhances lysosomal-mediated cell death, thus serving as an anticancer action." (PMID 34490237, 2021). "In both human breast cancer and mouse orthotopic breast tumours, TAMs had decreased TFEB expression, and in a mouse model where macrophages had a TFEB deficiency, breast tumour growth and metastasis were increased." (PMID 32745353, 2020). "Furthermore, these genes are transcriptionally regulated by TFEB and are associated with poor prognosis in breast cancer." (PMID 38926803, 2024). "Similarly, ER status alone is associated with differing TFEB expression levels as ER− patients show significantly higher expression of TFEB than those patients with ER+ breast cancer." (PMID 36372230, 2022). "Based on this, the object of this study was to see if quercetin might cause ferroptosis in breast cancer cell lines and to further explore its mechanism of action through the TFEB-lysosome pathway to induce ferroptosis." (PMID 35898781, 2022). "From this analysis of the role of the TFEB pathway in breast cancer chemoresistance, we reveal evidence that the increased expressions of TFEB and Beclin-1 are associated with a shorter survival period in patients suffering from invasive breast cancer who undergo chemotherapy." (PMID 34663249, 2021). "Interestingly, the recent research found that TFEB governs the expression of genes associated with DNA damage repair, apoptosis, and cell cycle in breast cancer cells, while lysosomal-autophagic function was independent of the prosurvival activity of TFEB in the cell." (PMID 38481802, 2024). "Furthermore, our results strongly indicate that the mechanisms governing the subcellular localization and biological activity of TFEB in response to Tam treatment are shared by all the breast cancer cell lines tested, irrespectively of their susceptibility or resistance to the drug." (PMID 38203629, 2023). "QUE enhanced expression of TFEB and nuclear transcription of TFEB and induced ferroptosis, thus killing breast cancer cells." (PMID 40552277, 2025). "An initial analysis of TFEB expression across various breast cancer subtypes revealed that TNBC displays a higher expression of TFEB than normal mammary tissue and other breast cancer subtypes." (PMID 39814550, 2025). "In recent breast cancer studies, Ursolic acid (UA) was found to enable transcription factor EB (TFEB) nuclear entry in a partial mammalian target of rapamycin (mTOR)-dependent manner and prevent its ubiquitination." (PMID 40723842, 2025). "Conversely, knockout of TFEB in macrophages enhanced breast cancer growth via promoting M2 polarization." (PMID 38287113, 2024). "This investigation aims at dissecting how TFEB is activated and contributes to Tam resistance in luminal A breast cancer cells." (PMID 38203629, 2023). "The evidence that lysosomal TRPML1 and TPCs drive the nuclear translocation of TFEB in Tam-resistant cells hints at an alternative strategy to circumvent endocrine resistance in breast cancer of the luminal A subtype." (PMID 38203629, 2023). "Rather, our observations totally agree with the previous data reporting that Tam is capable of affecting the subcellular localization of TFEB in both breast cancer cells and in fibroblasts." (PMID 38203629, 2023). "Quercetin promotes TFEB expression and nuclear transcription, induces the onset of iron death, and thus exerts a pharmacological effect on killing breast cancer cells." (PMID 35898781, 2022). "In breast cancer cells, quercetin treatment induced the onset of ferroptosis by promoting TFEB expression and nuclear transcription." (PMID 36467088, 2022).
breast carcinoma (continued). "Overall, various transcription factors including c-MYC, LXR, TFEB, etc., regulate the phenotype and function of TAMs in solid tumors such as lung cancer and breast cancer, thereby affecting tumor progression and metastasis." (PMID 36131942, 2022). "Gene expression data were obtained from The Cancer Genome Atlas breast cancer patient cohort, and TFEB expression was examined by histological and molecular subtypes." (PMID 36372230, 2022). "The antiproliferation effects of quercetin in breast cancer cell lines can be blocked by TFEB siRNA or chloroquine, an autophagy lysosomal inhibitor." (PMID 36355532, 2022). "TFEB gene expression is significantly higher in patients with ER-/HER2-breast cancer compared to patient samples that are ER+, HER2+, or ER+/HER+." (PMID 36372230, 2022). "For breast cancer, significant TFEB high expression and lysosomal biosynthesis in early breast cancer defined poor prognosis." (PMID 35531069, 2022). "Data from our work describe a novel regulator of breast DDCCs survival, EphB6, that modulates adaptation to lung microenvironment through the GSK3β-TFEB-lysosomal axis, providing potential novel liabilities of disseminated dormant breast cancer cells." (PMID 33802447, 2021). "This study aims to evaluate the prognostic impact of TFEB and its pathway in breast cancer chemoresistance." (PMID 34663249, 2021). "TFEB lysosomal direct targets are enriched in DDCCs in vivo and correlate with relapse in ER+ breast cancer patients." (PMID 33802447, 2021). "Our results confirm that an increased immunohistochemical TFEB expression correlates with a less favorable prognosis in women affected by breast cancer and treated with chemotherapy." (PMID 34663249, 2021). "Meanwhile, in the basal-like and HER2-enriched breast cancer subtypes TFEB and Beclin-1 seem to have a higher H-score than in the luminal molecular subtypes." (PMID 34663249, 2021). "TFEB expression is elevated in multiple types of human cancers, such as breast cancer, lung cancer, and pancreatic ductal adenocarcinoma." (PMID 34091590, 2021). "Enhanced TFEB expression correlates with aggressive clinical features and can be an unfavorable independent prognostic factor in breast cancer." (PMID 33732651, 2021). "The autophagy-independent function of TFEB was demonstrated in breast cancer, where TFEB inhibited apoptosis by regulating DNA repair mechanisms." (PMID 33912071, 2021). "It was concluded that TFEB is an important regulator of TAM in breast cancer; it controls TAM gene expression and function through multiple autophagy/lysosome-dependent and independent pathways." (PMID 33806255, 2021). "EphB6 depletion is accompanied by reduced TFEB-dependent genes transcription in indolent breast cancer cells from lungs and lung-organotypic system and decreased cytoplasmic area with Lysotracker-positive organelles in mouse and human models of DDCCs." (PMID 33802447, 2021). "Under standard culture conditions endogenous TFEB was localized to the cytoplasm in the breast cancer cell line MCF7, but was relocated to the nucleus on addition of the mTOR inhibitor Torin 1, indicating that in these cells mTOR controls TFEB localization." (PMID 29992949, 2018). "TNBC/basal-like tumors have higher levels of TFEB than the other breast cancer subtypes." (PMID 39814550, 2025). "Furthermore, co-IP experiments also validated the endogenous interactions of TRIM25 with UBC12 and TFEB in breast cancer cells." (PMID 38926803, 2024). "Due to this sort of self-amplification loop, the increased nuclear localization of TFEB induced by Tam might thus represent a factor concurring to its overexpression in breast cancer cells in the presence of the drug." (PMID 38203629, 2023). "Therefore, we are reasonably confident that lysosomal TPCs and TRPML1 are the primary sources of Ca2+ responsible for the nuclear translocation of TFEB in luminal A breast cancer cells." (PMID 38203629, 2023).
breast carcinoma (continued). "Consistently, the homogeneous pattern of TFEB relocation in the different breast cancer cell lines raises the possibility that this represents a sort of a common response of the transcription factor to Tam treatment of breast cancer cells of the luminal A subtype." (PMID 38203629, 2023). "Indeed, multiple studies correlate increased levels of TFEB with poor prognosis in several types of cancers, including glioblastoma, non-small lung cancer, breast carcinoma, and prostate cancer." (PMID 36888606, 2023). "TFEB controls the phenotype and function of TAMs through multiple autophagy/lysosome-dependent and independent pathways, thereby promoting breast tumor development; Conversely, activation of TFEB is expected to be a target for TAMs for tumor immunotherapy strategies including breast cancer." (PMID 36131942, 2022). "Our prior results found that TFEB was crucial for the survival of TNBC cells; however, limited studies have explored whether TFEB expression varies by molecular subtype in breast cancer patients." (PMID 36372230, 2022). "Further studies suggest that the mechanism of breast cancer inhibition by quercetin may be related to the promotion of lysosomal activation mediated by TFEB and subsequent ferritin degradation." (PMID 35898781, 2022). "In addition, research shows that transcription factor EB (TFEB) expression is significantly reduced in breast cancer." (PMID 36131942, 2022). "Regulators of TFEB function also show varied expression by breast cancer molecular subtype." (PMID 36372230, 2022). "In contrast, cell viability decreased with quercetin treatment, while both TFEB siRNA and chloroquine could block the lethal effect of quercetin on breast cancer cells (P < 0.001)." (PMID 35898781, 2022). "For instance, TFEB reduced the sensitivity of LoVo and HeLa cells to doxorubicin by inducing activation of autophagy, and it reduced the apoptosis of breast cancer cells in response to doxorubicin by repairing DNA damage." (PMID 34490237, 2021). "Furthermore, TFEB is highly expressed in glioblastoma, non-small lung cancer, pancreatic ductal adenocarcinoma, and breast carcinoma." (PMID 33732651, 2021). "Interestingly, breast cancer patients with a higher expression of TFEB targets show increased likelihood of developing relapses." (PMID 33670926, 2021). "Here, we demonstrate efficacy of the estradiol-derived TRPML1 antagonist EDME and analogs, which were rationally designed based on a profound SAR analysis of numerous tested steroidal compounds, on autophagy and TFEB translocation as well as breast cancer cell migration and invasion." (PMID 33859333, 2021). "This study’s main objective is to assess the prognostic role of TFEB, CARM1, SIRT1, and Beclin-1 in chemo-treated breast carcinoma and compare the TFEB, CARM1, SIRT1, and Beclin-1 expression with the methylation of PITX2 in breast cancer treated with chemotherapy." (PMID 34663249, 2021). "However, at the moment, only one article demonstrates a correlation between an increased TFEB expression in early breast cancer and a poorer prognosis." (PMID 34663249, 2021). "To examine whether there is a correlation between the level of Wnt signaling and TFEB mediated Wnt target genes in various types of cancer, we referred to TCGA for breast cancer and bladder cancer or GDC TCGA database for lung squamous cell carcinoma (LUSC)." (PMID 33753903, 2021). "TFEB can inhibit the apoptosis of breast cancer cells by activating DNA repair." (PMID 34490237, 2021). "In addition, Lamp2A has also been used as a marker to measure the lysosomal content in breast carcinomas and was correlated with increased activity of the transcription factor EB (TFEB)." (PMID 33643916, 2020). "Thus, MZF1 performs similar functions in breast cancer cells as TFEB, also known as a master regulator of the Coordinated Lysosomal Expression and Regulation (CLEAR) network, has in normal cells." (PMID 29396433, 2018).